TRIM29 (tripartite motif containing 29)
Diseases named in the same sentence as TRIM29 in open-access papers (continued):
Sharing a sentence is not in itself a finding about the gene and the disease.
viral myocarditis (continued). "Our findings offer insight into how cardiotropic viruses exploit TRIM29-regulated PERK signaling pathways to instigate viral myocarditis, suggesting that targeting the TRIM29-PERK axis could mitigate disease severity." (PMID 38664417, 2024). "Moreover, our findings suggest that the TRIM29-PERK axis holds promise as a viable therapeutic target for managing viral myocarditis." (PMID 38664417, 2024). "This positions TRIM29 as a viable target for host-directed immunotherapy of viral myocarditis." (PMID 38664417, 2024). "The loss of TRIM29 has been observed to reduce viral myocarditis in male mice by attenuating the PERK‐driven ER stress response, indicating that targeting the TRIM29–PERK axis may be a potential strategy for mitigating disease severity." (PMID 39188936, 2024). "Our groundbreaking discovery suggests that targeting the TRIM29-PERK axis could serve as a potent therapeutic strategy not only for viral myocarditis but also for other infectious diseases linked to PERK." (PMID 38664417, 2024). "Finally, we demonstrated that the PERK inhibitor GSK2656157 mitigated viral myocarditis by disrupting the TRIM29-PERK connection, thereby bolstering cardiac function, enhancing cardiac antiviral responses, and curbing inflammation and immunosuppressive mMDSC in vivo." (PMID 38664417, 2024). "TRIM29 can target NLRP6 and NLRP9b to modulate intestinal inflammation, mitigate viral myocarditis by attenuating PERK-driven ER stress, and negatively regulate type I IFN responses to RNA viruses." (PMID 39973927, 2025). "Next, we explored the molecular mechanisms by which TRIM29 mitigated PERK-mediated ER stress and ROS responses, thereby accentuating the pathogenesis of viral myocarditis." (PMID 38664417, 2024). "We also did not observe other miRs that may reduce myocarditis such as miR-122, which has been found to inhibit tripartite motif-containing protein 29 (TRIM29) where low levels of TRIM29 reduce viral replication and inflammation in a fulminant model of viral myocarditis." (PMID 39835120, 2024).
nasopharyngeal carcinoma (8 papers, 2016 to 2026). A carcinoma arising from the nasopharyngeal epithelium. "A previous study discovered that in nasopharyngeal carcinoma, TRIM29 overexpression can inhibit the expression of PTEN expression and activate the PI3K/AKT pathway." (PMID 34922544, 2021). "Knockdown of TRIM29 in airway epithelial cells enhances type I interferon production, and in human nasopharyngeal carcinoma cells results in almost complete Epstein-Barr virus clearance." (PMID 29038422, 2017). "Elevated TRIM29 expression is accompanied by more invasive phenotypes of malignancies, including bladder, cervical, colorectal, gastric, lung, ovarian, pancreatic, and thyroid cancers; osteosarcoma; and nasopharyngeal carcinoma (NPC)." (PMID 34988104, 2021). "Moreover, TRIM29 mRNA was significantly increased in patients with nasopharyngeal carcinoma of different pathological types." (PMID 32640423, 2020).
prostate carcinoma (7 papers, 2010 to 2025). A carcinoma that arises from epithelial cells of the prostate gland. "For example, TRIM29 is sometimes overexpressed and sometimes downregulated especially in prostate cancer." (PMID 33824865, 2021). "Similarly, in breast and prostate cancer, TRIM29 overexpression was found to have an inhibitory effect on tumor progression, and those patients with overexpression realized a better prognosis." (PMID 40362175, 2025). "However, TRIM29 appeared to have an inhibitory effect on other tumors, including breast and prostate cancers." (PMID 36568638, 2022). "Furthermore, the subcellular localization of TRIM29 is mainly found in the cytoplasm, consistent with TRIM29 acting as a tumor suppressor in breast and prostate cancers." (PMID 34988104, 2021). "However, in some tumours, especially in prostate cancer, TRIM29 is expressed at low levels." (PMID 34353343, 2021). "Besides, TRIM29 enhances tumor growth and metastasis in vivo, is highly expressed in many tumors, and could promote tumor growth, such as colon cancer and prostate cancer." (PMID 33824865, 2021). "In prostate cancer, TRIM29 is expressed in normal cells but not in cancer cells." (PMID 34988104, 2021).
cervical cancer (6 papers, 2016 to 2025). A primary or metastatic malignant neoplasm involving the cervix. "In conclusion, TRIM29 is overexpressed and associated with survival of early-stage cervical cancer, indicating that TRIM29 may be a potential prognostic biomarker and therapeutic target for cervical cancer." (PMID 27081037, 2016). "Further supporting ZEB1’s role, TRIM29 was downregulated in MTD-treated cells and its protein is associated with increased ZEB1 expression and EMT in cervical cancer cells." (PMID 37239838, 2023). "Recently, TRIM29 has been proved to decrease adhesion and promote invasion of cervical cancer cells through activating p63-mediated pathway." (PMID 27081037, 2016). "Dysregulation of TRIM29 has been reported to be involved in tumorigenesis, but the role of TRIM29 in cervical cancer is unclear." (PMID 27081037, 2016). "Wound healing assay showed that the decreased expression of TRIM29 by the two siRNAs led to slower migration rate in both cervical cancer cell lines." (PMID 27081037, 2016). "When endogenous TRIM29 expression was knocked down by siRNAs, cell proliferation, colony formation, migration and invasion in cervical cancer cell lines HeLa and SiHa were obviously inhibited." (PMID 27081037, 2016). "As expected, the TRIM29 protein expression was also markedly up-regulated in the four cervical cancer tissues, as judged by western blot." (PMID 27081037, 2016). "In this study, we reveal the extensive biological functions of TRIM29 in cervical cancer cells, such as promotion of proliferation, colony formation, migration, invasion and EMT of cervical cancer cells." (PMID 27081037, 2016). "In this study, we first examined TRIM29 expression and found that TRIM29 mRNA and protein expression was upregulated in cervical cancer tissues when compared with the matched adjacent cervical tissues." (PMID 27081037, 2016). "We further detected TRIM29 protein with immunohistochemistry in 150 paraffin-embedded samples from early-stage cervical cancer patients." (PMID 27081037, 2016). "Our results warrant further studies on the detailed mechanisms by which TRIM29 promotes tumor progression in cervical cancer." (PMID 27081037, 2016). "In the cervical cancer tissues, TRIM29 protein was primarily located in the cytoplasm and membrane of cervical cancer cells." (PMID 27081037, 2016). "Two siRNAs were designed against TRIM29 and transfected into cervical cancer cell lines Hela and SiHa." (PMID 27081037, 2016). "In this study, we focused on investigation of TRIM29 expression and its clinical significance and biological function in cervical cancer and also explored which cell signaling pathway was regulated by TRIM29 in cervical cancer cells." (PMID 27081037, 2016). "To investigate whether TRIM29 is dysregulated in human cervical cancer, we performed qRT-PCR and western blotting on four pairs of fresh cervical cancers (T) and matched adjacent cervical tissues (N)." (PMID 27081037, 2016). "This suggests that TRIM29 also may be potential biomarker for personalized therapy in cervical cancer." (PMID 27081037, 2016). "TRIM29 was proven to be an independent prognostic factor for cervical cancer patients." (PMID 27081037, 2016). "More important, transwell invasion assay indicated that inhibition of TRIM29 could significantly reduce the number of invaded cells in both cervical cancer cells." (PMID 27081037, 2016). "This suggests that higher expression of TRIM29 is always associated with poor survival in cervical cancer patients, no matter whether or not they have PLNM." (PMID 27081037, 2016). "Therefore, we carried out in vitro experiments to test whether TRIM29 enhances migration and invasion of cervical cancer cells." (PMID 27081037, 2016). "TRIM29 activates Wnt/β-catenin pathway contributing to EMT, cell proliferation, colony formation, and migration in cervical cancer." (PMID 40420099, 2025).
cervical cancer (continued). "This coactivator function of TRIM29 has been reported for MMP9 and p63, in non-small cell lung cancer and cervical cancer cells, respectively." (PMID 36690626, 2023). "Thus, we want to explore whether knockdown of TRIM29 can inhibit growth of cervical cancer cells." (PMID 27081037, 2016). "The result showed that TRIM29 knockdown upregulated E-cadherin and repressed N-cadherin and β-catenin, which clearly indicates inhibition of EMT in both cervical cancer cells." (PMID 27081037, 2016). "Therefore, TRIM29 may be a potential biomarker for evaluation of PLNM in cervical cancer patients." (PMID 27081037, 2016). "In this study, we demonstrate that TRIM29 is overexpressed in cervical cancer and correlated with PLNM, advanced FIGO stage, postoperative recurrence and poor survival of patients, suggesting TRIM29 plays an oncogenic role in cervical cancer." (PMID 27081037, 2016). "Furthermore, univariate analysis revealed that high TRIM29 expression, advanced FIGO Stage, and PLNM were significant predictors for poor OS and DFS in cervical cancer patients." (PMID 27081037, 2016). "Of those functions, promotion of cancer cell invasion by TRIM29 is in accordance with that reported by Masuda Y. More important, we elucidate that TRIM29 downregulation suppresses EMT, migration and invasion of cervical cancer cells by inhibiting Wnt/β-Catenin pathway." (PMID 27081037, 2016). "However, the clinical significance of TRIM29 in cervical cancer is not clear and its biological role in cervical cancer remains to be further elucidated." (PMID 27081037, 2016).
lung squamous cell carcinoma (6 papers, 2020 to 2023). "The results suggested that high TRIM29 expression in lung squamous cell carcinoma was significantly related to the short overall survival time." (PMID 32640423, 2020). "The results revealed that TRIM29 expression in lung squamous cell carcinoma tissues was significantly higher than those in the paired normal tissues (P<0.05)." (PMID 32640423, 2020). "In this study, our results revealed that TRIM29 can regulate autophagy of lung squamous cell carcinoma through the BECN1 gene." (PMID 32640423, 2020). "In summary, TRIM29 expression in lung squamous cell carcinoma tissue was higher than those in the paired normal tissues." (PMID 32640423, 2020). "In order to further probe the biological function of TRIM29 in lung squamous cell carcinoma cells, we have studied TRIM29 expressions in six selected cell lines, including HNBE, HTB-182, CRL-5889, SK-MES-1, NCL-H520, and NCL-H1915." (PMID 32640423, 2020). "Meanwhile, high TRIM29 expression in lung squamous cell carcinoma tissue was closely related to the poor overall survival time." (PMID 32640423, 2020). "In this study, our results suggested that TRIM29 was highly expressed in lung squamous cell carcinoma tissues." (PMID 32640423, 2020). "Firstly, we examined the expression of TRIM29 in 30 lung squamous cell carcinoma tissues and the paired normal tissues with immunohistochemical staining, western blot, and qRT-PCR analysis." (PMID 32640423, 2020). "High TRIM29 expression in lung squamous cell carcinoma tissues was an independent factor of overall survival." (PMID 32640423, 2020). "Moreover, the downregulation of TRIM29 has potent antitumor activity and chemosensitizing effects in human lung squamous cell carcinoma." (PMID 37516854, 2023). "TRIM29 is a selective regulator of the activation of alveolar macrophages and the production of proinflammatory cytokines in the lungs and is found to mediate lung squamous cell carcinoma cell metastasis by regulating autophagic degradation of E-cadherin." (PMID 34993203, 2021). "In summary, we demonstrated that high TRIM29 expression could be detected in lung squamous cell carcinoma, which was closely related to the OS of patients." (PMID 32640423, 2020). "In addition, we had demonstrated the detailed molecular mechanisms of TRIM29 molecular in lung squamous cell carcinoma." (PMID 32640423, 2020). "TRIM29 could promote proliferation, invasion, and migration in lung squamous cell carcinoma by regulating E-cadherin autophagy degradation." (PMID 32640423, 2020). "However, there is still poor evidence about the role of TRIM29 in lung squamous cell carcinoma." (PMID 32640423, 2020). "IKKα suppresses TRIM29 and p63 in an epigenetic manner to prevent lung squamous cell carcinoma (SCC) development, but TP73-AS1 serves as a molecular sponge for miR-34a-5p to prevent TRIM29 suppression." (PMID 34988104, 2021). "For immunohistochemical staining analysis, the results suggested that TRIM29 expression in lung squamous cell carcinoma tissues was significantly higher than that in the paired normal tissues." (PMID 32640423, 2020). "The results of western blot and qRT-PCR analysis indicated that TRIM29 expression in lung squamous cell carcinoma tissues was significantly higher than that in the paired normal tissues." (PMID 32640423, 2020).
non-small cell lung carcinoma (6 papers, 2019 to 2025). A group of at least three distinct histological types of lung cancer, including non-small cell squamous cell carcinoma, adenocarcinoma, and large cell carcinoma. "In non-small cell lung cancer, TRIM29 contributes to oncogenesis by modulation of cell cycle-related proteins." (PMID 40420099, 2025).
thyroid cancer (5 papers, 2020 to 2022). "In thyroid carcinoma, high expression of TRIM29 activates PI3K/AKT signaling, which circumvents cell cycle arrest at the G0/G1 phase and enhances cancer cell resistance to chemotherapy." (PMID 34988104, 2021). "In thyroid cancer, TRIM29 was observed as a oncogene to promote cell proliferation via PI3K/AKT signaling pathway and correlate with poor prognosis." (PMID 32994394, 2020). "Although our study revealed a vital role of LINC00324/miR-195-5p/TRIM29 in the progression of PTC, questions remain concerning the relevance of LINC00324/miR-195-5p/TRIM29 axis in other subtypes of thyroid carcinoma." (PMID 33318312, 2020). "In our previous study, we reported high levels of TRIM29 in PTC, and that TRIM29 depletion suppressed the proliferative and invasive capabilities of PTC cells; findings that suggest a cancer-promotion function of TRIM29 in thyroid carcinoma." (PMID 33318312, 2020). "Moreover, lncRNA HOXA11-AS involves the tumorigenesis of thyroid cancer by protecting TRIM29 by inhibiting miR-761 activity." (PMID 35443670, 2022). "However, the current study demonstrated that TRIM29 obviously promoted the migration/invasion ability but the effect on proliferation of thyroid cancer cells was limited." (PMID 32994394, 2020). "Therefore, additional studies are needed to assess whether the LINC00324/miR-195-5p/TRIM29 axis is restricted to PTC or if it extends to other subtypes of thyroid cancer." (PMID 33318312, 2020). "As a member of the tripartite motif protein family, TRIM29 has been shown to play oncogenic roles in various cancers, including CRC, and activate the PI3K/AKT signaling pathway in thyroid cancer." (PMID 34922544, 2021). "RNA sequence demonstrated that several long non-coding RNAs (LncRNAs) were downregulated by TRIM29 knockdown, and LncRNA CYTOR was screened as online database exhibited that CYTOR was positively co-expressed with TRIM29 and FN1 in thyroid cancer tissues." (PMID 32994394, 2020). "Online database (starbase.sysu.edu.cn) also demonstrated a negative co-expression between TRIM29 and miR-873-5p in thyroid cancer tissues." (PMID 32994394, 2020). "Online database (starbase.sysu.edu.cn) also showed a negative co-expression between TRIM29 and miR-873-3p in thyroid cancer tissues." (PMID 32994394, 2020). "The database GEPIA also revealed a positive co-expression of TRIM29 and FN1 in thyroid cancer." (PMID 32994394, 2020).
ataxia telangiectasia (4 papers, 2013 to 2020). Ataxia-telangiectasia is the association of severe combined immunodeficiency (affecting mainly the humoral immune response) with progressive cerebellar ataxia. "The researcher had cloned TRIM29 for the first time when looking for genes that cause ataxia-telangiectasia (AT) augmentation." (PMID 32640423, 2020). "ATDC, also known as TRIM29, was initially identified in a search for the gene responsible for the genetic disorder ataxia-telangiectasia and was found to possess radiosensitivity suppressor functions." (PMID 23776433, 2013). "A further member of TRIM family proteins with a clear tumorigenic role in CRC is TRIM29 also known as “AT group D complementing” (ATDC) gene product originally identified as a gene with a pathogenic role in the autosomal-recessive disorder Ataxia telangiectasia." (PMID 33066016, 2020).
breast tumors (4 papers, 2013 to 2025). "Similarly, TRIM29 is often silenced in breast tumors due to aberrant gene hypermethylation and acts as a tumor suppressor through its ability to suppress EMT." (PMID 40943642, 2025). "Interestingly, TRIM29 regulation in breast tumors clustered according to the PAM50 classification." (PMID 24651077, 2014).